MIR324 (microRNA 324)
Synonyms: hsa-mir-324; MIRN324; mir-324
Gene: MicroRNA gene on chromosome 17 (7,223,297 to 7,223,379, reverse strand). Ensembl gene ENSG00000199053.
Gene Ontology:
Biological process: cellular response to leukemia inhibitory factor; long-term synaptic potentiation; miRNA-mediated post-transcriptional gene silencing; positive regulation of cytokine production involved in inflammatory response; sensory perception of sound
Cellular component: RISC complex
Homologues: Orthologues: chimpanzee ptr-mir-324 (100% identical), macaque mml-mir-324 (100% identical).
Diseases named in the same sentence as MIR324 in open-access papers:
MIR324 is named in the same sentence as 2 diseases in open-access papers, as found by Europe PMC text mining. Sharing a sentence is not in itself a finding about the gene and the disease. The quoted sentences say what the papers report.
Anxiety (1 paper, 2023). Intense feelings of nervousness, tension, or panic often arise in response to interpersonal stresses. "The decreased latency to dig observed in Mir324 KO mice during a marble burying task may indicate changes in anxiety behavior." (PMID 38082035, 2023).
MIR324 also shares sentences with these, for which no sentence is quoted: epilepsy (1 paper).